NLRP3 (NLR family pyrin domain containing 3)
Diseases named in the same sentence as NLRP3 in open-access papers (continued):
Sharing a sentence is not in itself a finding about the gene and the disease.
Cognitive impairment (continued). "Another study also reported that aged mice treated with MCC950 (NLRP3 inflammasome inhibitor) could provide neuroprotective effects against pyroptosis by activating the inflammasome, thus reducing cognitive impairment." (PMID 31781266, 2019). "Specifically, we found that the NLRP3 inflammasome might contribute to isoflurane-induced neuroinflammation and cognitive impairment in the aged mice." (PMID 29665808, 2018). "NLRP3 priming status in aged mouse brain may be involved in isoflurane-induced hippocampal inflammation and cognitive impairment." (PMID 29665808, 2018). "We found that isoflurane GA caused upregulations of hippocampal NLRP3, cleaved caspase-1, interleukin-1β (IL-1β), and IL-18 and the activation of pyroptosis, which is NLRP3 inflammasome-dependent; this consequently gave rise to neuronal damage and cognitive impairment in aged mice." (PMID 30524241, 2018). "S/L attenuated AlCl3-induced cognitive deficits, restored antioxidant status, suppressed neuroinflammation, improved cholinergic indices, modulated apoptotic signaling, and downregulated amyloidogenic and NLRP3 inflammasome markers, consistent with histological evidence of neuronal preservation." (PMID 41471381, 2025). "However, whether gut microbiota modulates CNS autoimmunity and cognitive impairment by influencing NLRP3 inflammasome‐related molecules in MS remains unclear." (PMID 40050112, 2025). "Therefore, we evaluated if inhibition of NLRP3 inflammasome activation could reduce these affective and cognitive disorders." (PMID 40002330, 2025). "Conversely, dysbiosis-induced activation of the NLRP3 inflammasome, a central component of the innate immune system, links intestinal imbalance to systemic and neuroinflammatory cascades that contribute to cognitive impairment and neurodegenerative diseases, including Alzheimer’s disease." (PMID 41458114, 2025). "The activation of NLRP3 recruits the adaptor molecule ASC and triggers the release of the pro-inflammatory cytokines IL-1β and IL-18, processed by caspase (casp-1), which compromises brain homeostasis and is associated with cognitive deficits and depressive-like behavior." (PMID 41488618, 2025). "Our findings suggest that A. muciniphila may modulate neuroinflammation and cognitive impairment via hippocampal NLRP3‐mediated neuroinflammation, and peripheral T cell response might modulate the relationship between intestinal microbiota and cognitive behavior in EAE mice." (PMID 40050112, 2025). "Moreover, NLRP3 inflammasomes were activated by anesthesia and surgery, along with cognitive impairment, microglia activation, increased pro-inflammatory cytokines expression, and impaired mitophagic flux, which were inverse by triggering receptor expressed on myeloid cells 2 (TREM2) in mice." (PMID 37548945, 2024). "Therefore, we speculated that the activation of NLRP3 inflammasome in astrocytes was a basis for neuroinflammation and cognitive impairment." (PMID 38664193, 2024). "Additionally, NLRP3 levels were negatively correlated with gwBTV, further substantiating the connection between inflammatory processes and brain structure deterioration in cognitive impairment." (PMID 39109268, 2024). "These cognitive deficits were associated with significant increases in the levels of NLRP3, ASC, caspase-1, phosphorylated IκB-α, and p65 levels in the hippocampus, emphasizing the pivotal role of the NLRP3 inflammasome in both surgery and anesthesia-induced POCD." (PMID 39411285, 2024). "Therefore, we suggest that FG may play an anti-inflammatory role by inhibiting the activation of NLRP3/NF-κB pathway, thereby reducing HU-induced cognitive impairment." (PMID 37205911, 2023). "It was reported that NLRP3 inflammasome-mediated pyroptosis directly led to cognitive impairment in PND mice model induced by isoflurane, and NLRP3 inflammasome inhibitor MCC950 could inhibit overactivated pyroptosis and exert a neuroprotective effect, thus improving cognitive impairment." (PMID 37332874, 2023).
Cognitive impairment (continued). "Moreover, astrocyte-specific NLRP3 knockout mice reversed TF-induced impulsive-like and cognitive impairment behaviors, decreased GABA levels in reactive astrocytes, ameliorated NLRP3-associated inflammatory responses during the early stage, and restored neuronal degeneration in the hippocampus." (PMID 37434240, 2023). "Therefore, our findings suggest that the NLRP3 inflammasome may be a new therapeutic target for cognitive impairment, and that targeting the NLRP3/Caspase-1/IL-1β signaling axis is a promising approach for the treatment of postoperative inflammation." (PMID 36934348, 2023). "Interestingly, our experiments demonstrated that KXS could alleviate neuroinflammation mediated by NLRP3 inflammasome activation which improved cognitive impairment in APP/PS1 mice." (PMID 36918872, 2023). "Moreover, astrocyte-specific NLRP3 knockout mice reversed TF-induced impulsive-like and cognitive impairment behaviors, decreased GABA levels in reactive astrocytes, ameliorated NLRP3-associated inflammatory responses at the early stage, and restored neuronal degeneration in the hippocampus." (PMID 37434240, 2023). "Therefore, targeting the NLRP3-Caspase-1-IL-1β signaling axis may be an important way to improve cognitive impairment, although the exact activation mechanism is unknown." (PMID 36934348, 2023). "In addition, colitis could upregulate neuroinflammation, Aβ deposition, and cognitive impairment, but this effect could be mitigated by kickout of NLRP3." (PMID 36688154, 2022). "Fisetin‐blocked NLRP3 inflammasome activation via promoting mitophagy in CMECs may suppress the secretion of IL‐1β into CNS, reduce neuroinflammation, and contribute to the amelioration of cognitive impairment." (PMID 34837343, 2022). "Immediately following the third phase in 2020, more attention was paid to the feasibility of NLRP3 inflammasome as a therapeutic target, so keywords regarding the evaluation of the efficacy to treat diseases became popular, such as “functional recovery” and “cognitive impairment”." (PMID 36160384, 2022). "In summary, the current results showed that neuroinflammation and cognitive impairment after surgery are related to the activation of the P2X4/NLRP3 signaling pathway in the hippocampus, and inhibiting this pathway may be a promising method to prevent and treat PND." (PMID 35153623, 2022). "Collectively, fisetin‐blocked NLRP3 inflammasome activation via promoting mitophagy in CMECs may suppress the secretion of IL‐1β into CNS, reduce neuroinflammation, and contribute to the amelioration of cognitive impairment." (PMID 34837343, 2022). "Although our findings did not support NLRP3 confer susceptibility to schizophrenia, NLRP3 may be a risk factor for cognitive impairment, especially attention deficit in this disorder." (PMID 34956329, 2021). "Therefore, inhibition of p-NR1 (Ser896) levels by HMGB1 may mediate NLRP3 inflammasome-induced cognitive impairment." (PMID 34666797, 2021). "Therefore, EA stimulation at GV 20 and GV 24 acupoints may be a potential alternative therapy for deterring cognitive deficits in AD through suppression of NLRP3 inflammasome activation." (PMID 33505459, 2021). "Moreover, we assessed the effect of NLRP3 inflammasome on EAE-related cognitive deficits." (PMID 32415059, 2020). "Therefore, to assess the role of CCH in VaD-related brain abnormalities and cognitive impairment, we investigated memory behaviors, the cholinergic system, myelin maintenance, synaptic protein expressions, gliosis, and NLRP3 inflammasome signaling in the BCCAo rat model." (PMID 31766248, 2019). "Thus, we hypothesized that the NLRP3/caspase-1 pathway is involved in NLRP3-mediated pyroptosis, maturation and release of inflammatory cytokines, and cognitive deficits in SAE." (PMID 30276509, 2019).
Cognitive impairment (continued). "The present results suggest that hypercapnia-induced IL-1β overproduction via activating the NLRP3 inflammasome by hypoxia-activated microglia may augment neuroinflammation, increase neuronal cell death, and contribute to the pathogenesis of cognitive impairments." (PMID 29304864, 2018). "Our data demonstrate that pyroptosis is involved in NLRP3 inflammasome-mediated isoflurane-induced cognitive impairment in aged mice and suggest that inhibiting the NLRP3 inflammasome with MCC950 may have clinically therapeutic benefits for elderly patients undertaking GA." (PMID 30524241, 2018). "Conversely, downregulation of microglial NLRP3 inhibited caspase-1 activation and pyroptosis, reduced release of IL-1β, improved AHN, and rescued cognitive deficits in DE mouse model." (PMID 41862685, 2026). "As NLRP3 is a key immune regulator, inhibitors of NLRP3 such as MCC950, cy-09, and OLT1177 are proven to have neuroprotective effects and alleviate cognitive impairment, and also support cognitive development in AD." (PMID 41516057, 2025). "Our study uniquely demonstrates that HFD concurrently aggravates hippocampal NLRP3 activation and ALP impairment in 3xTg‐AD mice, driving cognitive deficits." (PMID 40589337, 2025). "70% showed cognitive impairment (WMS-R score < 50) after MECT; this group showed significantly higher post-ECT levels of NLRP3, IL-18, and NF-κB compared to cognitively preserved participants (p < 0.05)." (PMID 40969698, 2025). "These elevations were blocked by the administration of SB332235 which also restores motor and cognitive deficits, indicating a notable protective effect of SB332235 against NLRP3 inflammasome activation after TBI." (PMID 37702890, 2024). "Inhibiting NLRP3 using MCC950 or caspase-1 using Ac-YV AD-CMK can reduce mortality, reverse cognitive impairment, and salvage neuronal damage." (PMID 39027435, 2024). "Curcumin improves cognitive impairment by inhibiting neuroinflammation-induced activation of microglia, modulating the TREM2/TLR4/NF-κB pathway, and reducing NLRP3-dependent pyroptosis." (PMID 38020781, 2023). "Excessive activation of inflammatory pathways such as TLR4/NF-κB/NLRP3 and TLR4/Akt/mTOR promotes an increase in the central nervous system inflammatory response and participates in the occurrence and development of cognitive impairment." (PMID 37576498, 2023). "Accumulating studies have suggested that neuroinflammation can lead to neuronal damage, synaptic injury and cognitive deficits in CCH, and it has also been reported that the levels of the NLRP3 inflammasome are significantly increased in CCH." (PMID 37932279, 2023). "Blocking the NLRP3 inflammasome pathway with the caspase-1 specific inhibitor AC-YVAD-CMK prevents motor and cognitive impairments in HIBD models." (PMID 37620837, 2023). "Therefore, inhibition of NLRP3 may be a major strategy for the treatment of cognitive impairment." (PMID 37915104, 2023). "In conclusion, the present results suggest that fisetin‐blocked NLRP3 inflammasome activation via promoting mitophagy in CMECs may suppress the secretion of IL‐1β into the CNS, reduce neuroinflammation, and contribute to the amelioration of cognitive impairment." (PMID 34837343, 2022). "DEX administration improved the cognitive impairment and reduced pro-inflammatory cytokines in the POCD model by regulating NLRP3 and ASC expression." (PMID 35955939, 2022). "Fourthly, the contributions of NLRP3 and GSDMD to the migraine-related cognitive impairment need to be further investigated using targeted therapeutic compounds." (PMID 35780081, 2022). "The ATOR treatment can also potentiate the neuroinflammatory process via the activation of NLRP3 and its subsequent mediator IL1B-inducing cognitive impairment." (PMID 35335908, 2022).
Cognitive impairment (continued). "Overexpressing HSPB8 in the hippocampi inhibited NLRP3 inflammasome activation via dephosphorylating DRP1 at the phosphorylated site Ser616 (p-Drp1S616), reduced oxidative stress, and ultimately relieved cognitive impairments." (PMID 35958024, 2022). "HJ22 is a derivative of piperine, a black pepper alkaloid, heals cognitive impairment and exert cytoprotection through KEAP1/Nrf2/ARE activation and NLRP3 inhibition." (PMID 35418995, 2022). "Specific inhibition of NLRP3 with MCC950 exerts potent protective effects on NEC and NEC-induced acute brain damage as well as long-term cognitive impairment, therefore opening up a new therapeutic approach for infants suffering from NEC." (PMID 33676524, 2021). "Consistently, ELS exposure increased expression of NLRP3 inflammasome proteins and anxiety-like behavior in adolescent rats, and NLRP3 inflammasome inhibition mitigated ELS-induced cognitive impairment in adult mice." (PMID 34683104, 2021). "The behavioral results suggested that the NLRP3 KO mice were resistant to CKD-induced learning and memory dysfunction, as well as that NLRP3-mediated neuroinflammation was crucially involved in cognitive impairment in CKD mice." (PMID 34572437, 2021). "Our data showed that the NLRP3 inflammasome continues to be activated along with high HMGB1 levels in the model at 4–8 weeks after TBI, which is consistent with cognitive impairment and LTP inhibition." (PMID 34666797, 2021). "In our study, knocking out NLRP3, similar to the results in the glycyrrhizin-treatment group, improved LTP and TBI-induced cognitive impairment." (PMID 34666797, 2021). "However, the role of NLRP3 inflammasome in CKD-related cognitive impairment remains unclear." (PMID 34572437, 2021). "By using the NLRP3-knockout TBI model, we found that the continuous activation of the NLRP3 inflammasome and high mobility group box 1 (HMGB1) release were closely related to cognitive impairment." (PMID 34666797, 2021). "MCC950, an NLRP3 inhibitor, or Ac-YVAD-CMK ameliorates neuronal pyroptosis and neuroinflammation in the hippocampus, thereby decreasing cognitive impairment." (PMID 32046097, 2020). "Our study provides evidence to show that harmine can mitigate cognitive impairment in STZ-induced diabetic rats and exert neuroprotective effects through inhibiting NLRP3 inflammasome activation and enhancing the BDNF/TrkB signaling pathway." (PMID 32425784, 2020). "A specific small molecule inhibitor of NLRP3, MCC950, suppresses isoflurane-induced proinflammatory cytokines’secretion to weaken cognitive impairment." (PMID 32093389, 2020). "In this study, we show that administration of either the NLRP3-inhibitor MCC950 or the caspase-1 inhibitor Ac-YVAD-CMK reduces mortality, reverses cognitive impairments, and rescues neuronal damages in mice that have undergone CLP." (PMID 30276509, 2019). "Notably, restoration of this pathway by administration of MCC950 or Ac-YVAD-CMK could reduce NLRP3-mediated overactivation of neuronal pyroptosis, downregulate the expression of mature IL-1β and IL-18, rescue neuronal damage, and reduce cognitive impairments in SAE mice." (PMID 30276509, 2019). "FN has also suppressed cognitive impairment in diabetic mice, possibly through the downregulation of TLR4/NF-κB signaling and NLRP3 inflammasome." (PMID 31561418, 2019). "This study explores the protective effects of the NLRP3 inflammasome inhibitor MCC950 on pyroptosis and cognitive impairment in aged mice exposed to isoflurane." (PMID 30524241, 2018). "Both IF and exercise partially reversed cognitive impairments by reducing sAβ and oxidative stress, increasing BHB, suppressing NF-κB/NLRP3 signaling, and restoring BDNF (p < 0.05), while fasted-state exercise produced significantly larger effects than either intervention alone (p < 0.05)." (PMID 42152587, 2026).
Cognitive impairment (continued). "In an isoflurane-induced PND mouse model, aged mice exhibited increased hippocampal expression of NLRP3 and caspase-1 along with cognitive deficits, whereas young mice showed no such changes." (PMID 40914484, 2025). "Interestingly, pharmacological inhibition of NLRP3 by OLT1177 ameliorates Aβ accumulation and cognitive impairment in an AD mouse model." (PMID 41306975, 2025). "Increased NLRP3 activation and IL-1β expression have been detected in the hippocampus and amygdala of HFD-fed mice, which may contribute significantly to cognitive impairment." (PMID 41194915, 2025). "Moreover, the deletion of the NLRP3 gene in APP/PS1 mice reduces Aβ deposition and alleviates cognitive impairment." (PMID 39861665, 2024). "More importantly, the MWM study showed that the protective effect of JNK‐IN‐8 on cognitive impairment was blocked by the NLRP3 activator nigericin, suggesting that JNK‐IN‐8 treatment improved ARDS‐induced cognitive impairment by suppressing the JNK/NF‐κB‐mediated NLRP3 inflammasome." (PMID 36987783, 2023). "In contrast, inhibitors of the NLRP3 inflammasome, such as MCC950, cy-09 and OLT1177, are neuroprotective and may alleviate cognitive impairment, leading to improved cognitive function in AD." (PMID 37915104, 2023). "MCC950 also improved cognitive impairment in the surgery model but did not regulate NLRP3 expression." (PMID 35955939, 2022). "It was reported that the administration of MCC950 could inhibit the level of NLRP3, ASC, and IL-1β in hippocampus and ameliorate cognitive impairment in db/db mice." (PMID 35955939, 2022). "Recently, Guo and colleagues hypothesized that NLRP3 induction in visceral adipose tissue (VAT) could initiate central microglial activation and cognitive impairment by increasing IL-1β." (PMID 34070553, 2021). "We further explored whether a selective NLRP3 inhibitor MCC950 could alleviate NEC-related intestinal and neuroinflammation, especially long-term cognitive impairments, therefore providing a new potential therapeutic strategy for NEC." (PMID 33676524, 2021). "Accordingly, components of NLRP3 inflammasome such as increased levels of cleaved caspase-1 and IL-1β were detected in the serum of early AD patients or patients with mild cognitive impairment (MCI) as compared to non-demented and age-matched controls." (PMID 33499208, 2021). "NU9056 might effectively alleviate the cognitive impairment, emotional disorder, inflammation, and BBB dysfunction of the experimental SAE by inhibiting the NLRP3 inflammasome." (PMID 34327209, 2021). "This study was aimed to explore whether hypercapnia would partake in increasing IL-1β secretion via activating the NLRP3 (NLR family, pyrin domain-containing 3) inflammasome in the hypoxic CNS and in aggravating cognitive impairment." (PMID 29304864, 2018). "Interestingly, pretreatment with NLRP3 inflammasome inhibitor MCC950 not only provided a neuroprotective effect against the inflammasome activation but also ameliorated pyroptosis and cognitive impairment in aged mice exposed to isoflurane." (PMID 30524241, 2018). "Our results collectively suggest that NLRP3 inflammasome-dependent pyroptosis plays a negative role in the pathogenesis of isoflurane-induced cognitive impairment in aged mice and that MCC950 acts as a potential therapeutic compound for the treatment of POCD." (PMID 30524241, 2018). "The relative expression levels of NLRP3 (p < 0.05), ASC (p < 0.05), and Caspase-1 (p< 0.05) in the jejunum of the model group were significantly increased, indicating that intestinal inflammation was increased in mice with cognitive impairment induced by sleep deprivation." (PMID 40232008, 2025). "In addition, decreases in the expression levels of ASC, Caspase-1, and IL-1β/IL-18 have been shown to alleviate the cognitive impairment of gerbils after I/R, and ASC exacerbates ischemic neurological deficits and inflammatory reactions in an NLRP3-dependent manner." (PMID 38441564, 2024).